CFTR (CF transmembrane conductance regulator)
Diseases named in the same sentence as CFTR in open-access papers (continued):
Sharing a sentence is not in itself a finding about the gene and the disease.
cystic fibrosis (continued). "Cystic fibrosis is a multi-organ disease caused by mutations in the CFTR gene, leading to progressive organ damage." (PMID 41471270, 2025). "The landscape of cystic fibrosis has undergone a profound transformation following the advent of Cystic Fibrosis Transmembrane Regulator (CFTR) modulator therapies, which target the underlying genetic defect rather than solely managing symptoms." (PMID 41154689, 2025). "Cystic fibrosis is a genetic disease caused by mutations in the cystic fibrosis transmembrane conductance regulator (CFTR) ion channel, which normally transports chloride ions into the extracellular space (1, –, 3)." (PMID 40172197, 2025). "CF is caused by mutations in the Cystic Fibrosis Transmembrane Conductance Regulator (CFTR) gene that lead to pathologically thickened endobronchial mucus and impaired mucociliary clearance, which favors pulmonary inflammation and infection." (PMID 40171501, 2025). "Diagnosing CF involves sweat chloride testing and cystic fibrosis transmembrane conductance regulator (CFTR) mutation analysis." (PMID 40128832, 2025). "Cystic fibrosis, a genetic disorder characterized by mutations in the CFTR gene, has seen significant advances in treatment through cutting-edge approaches such as gene therapy and personalized medicine." (PMID 40282362, 2025). "Cystic fibrosis is an autosomal recessive genetic disease, caused by mutations in the gene encoding the CF transmembrane conductance regulator channel (CFTR)." (PMID 40249250, 2025). "Cystic Fibrosis is a multiorgan disease caused by mutations in the CFTR gene, leading to chronic pulmonary infections and hyperinflammation." (PMID 40501816, 2025). "Cystic fibrosis is a monogenic disease caused by mutations in the CF transmembrane regulator (CFTR) gene." (PMID 40298413, 2025). "Cystic fibrosis is an autosomal recessive disorder primarily caused by mutations in the cystic fibrosis transmembrane conductance regulator (CFTR) gene." (PMID 40356890, 2025). "Cystic fibrosis is a genetic disorder caused by a mutation in the gene encoding the cystic fibrosis transmembrane conductance regulator (CFTR), leading to dehydrated, thickened mucous." (PMID 40283411, 2025). "Cystic fibrosis is a rare disease caused by mutations in the gene encoding the CF transmembrane conductance regulator (CFTR), a chloride channel with an important role in the airways." (PMID 40100363, 2025). "Cystic fibrosis is an autosomal recessive genetic disorder caused by pathogenic variants of the gene encoding cystic fibrosis transmembrane conductance regulator (CFTR)." (PMID 41586257, 2025). "Cystic fibrosis is caused by mutations in the CF transmembrane conductance regular (CFTR) gene and is characterised by recurrent respiratory bacterial and fungal infections." (PMID 39997410, 2025). "In 1989, Collins and Tsui identified the underlying cause of CF as a mutation in the CFTR gene (Cystic Fibrosis Transmembrane Conductance Regulator)." (PMID 40791795, 2025). "Cystic fibrosis is a genetic disease caused by mutations in the CF transmembrane conductance regulator (CFTR) gene, leading to chronic, unresolved inflammation of the airways due to uncontrolled recruitment of polymorphonuclear leukocytes (PMNs)." (PMID 40029006, 2025). "Cystic fibrosis is a hereditary genetic disorder caused by autosomal recessive mutations in the CF transmembrane conductance regulator (CFTR) gene." (PMID 41003177, 2025). "Cystic fibrosis is a genetic disorder caused by mutations in cystic fibrosis transmembrane conductance regulator (CFTR) gene, leading to impaired chloride ion transport across epithelial cell membranes." (PMID 41324062, 2025). "Cystic fibrosis is a genetic disease caused by mutations in the cystic fibrosis transmembrane conductance regulator (CFTR) gene, resulting in CFTR protein dysfunction." (PMID 40042272, 2025).
cystic fibrosis (continued). "CF is caused by mutations in the gene encoding the cyclic AMP-dependent Cl− channel named Cystic Fibrosis Transmembrane Conductance Regulator (CFTR)." (PMID 40862723, 2025). "Cystic fibrosis is an autosomal recessive disorder caused by mutations in the CFTR gene, leading to impaired chloride transport, thickened mucus, and multiorgan dysfunction." (PMID 40842499, 2025). "For example, individuals carrying loss of function alleles in CFTR (leading to cystic fibrosis) or in PCSK9 (reducing LDL cholesterol and protecting against heart disease) may exhibit different sets of modifying loci than those relevant to individuals without the major effect variant." (PMID 41279859, 2025). "Most of the CF patients followed at referral centers in Brazil have class I or II mutations in the cystic fibrosis transmembrane conductance regulator (CFTR) gene, all of which are associated with severe forms of CF that lead to multisystem involvement." (PMID 40531733, 2025). "CF is caused by mutations in the Cystic Fibrosis Transmembrane conductance Regulator (CFTR) chloride channel, which is expressed in certain epithelia, including the respiratory tract, pancreas, and the gut2-4." (PMID 40631082, 2025). "Cystic fibrosis arises from mutations in the cystic fibrosis transmembrane conductance regulator (CFTR) gene." (PMID 40144832, 2025). "Cystic fibrosis is a monogenic disorder caused by mutations in the CFTR gene, which encodes the cystic fibrosis transmembrane conductance regulator (CFTR) protein." (PMID 40573412, 2025). "In ClinVar, the CFTR gene is related to cystic fibrosis, the BRCA2 gene is associated with breast cancer and breast-ovarian cancer syndrome, and the C3 gene is associated with complement component 3 deficiency." (PMID 39796280, 2025). "Cystic fibrosis is an hereditary genetic disease caused by a dysregulation of the cystic fibrosis transmembrane regulator (CFTR) gene by a chronic hyperinflammatory state and by frequent and severe bacterial infection of the lungs." (PMID 39846681, 2025). "Cystic fibrosis is a monogenic disorder caused by mutations in the Cystic Fibrosis Transmembrane Conductance Regulator (CFTR) gene on chromosome 7, characterized by substantial clinical heterogeneity." (PMID 40142300, 2025). "The vast majority of people with cystic fibrosis have a deletion of Phe508, which results in severe functional deficiencies in the CFTR protein." (PMID 40007443, 2025). "Cystic fibrosis results from mutations in the gene encoding the cystic fibrosis transmembrane conductance regulator (CFTR)." (PMID 39996724, 2025). "Cystic fibrosis is a multisystemic genetic disorder caused by dysfunctional CF transmembrane conductance regulator (CFTR) protein, leading to impaired chloride and bicarbonate transport." (PMID 40869482, 2025). "Cystic fibrosis is a fatal inherited disease caused by mutations in the cystic fibrosis transmembrane conductance regulator (CFTR) gene, which is inherited in an autosomal recessive manner." (PMID 39939583, 2025). "Pathogenic mutations of the CFTR channel cause the disease cystic fibrosis, the most common lethal genetic disorder in the Caucasian population which affects ∼100,000 patients worldwide." (PMID 40785054, 2025). "The cause of CF are mutations in the Cystic Fibrosis Transmembrane Conductance Regulator (CFTR) gene, which impair the function of the CFTR protein through various mechanisms such as misfolding, defective processing or reduced channel activity." (PMID 41416220, 2025). "Cystic fibrosis is a multiorgan genetic disorder caused by a deficiency or malfunction of the CF transmembrane conductance regulator (CFTR) protein, leading to a reduced life expectancy of roughly 40 years due to the gradual deterioration of lung function." (PMID 41377908, 2025). "The Cystic Fibrosis Foundation recommends that CF newborn screening programs screen for all CF-causing CFTR variants in CFTR2." (PMID 40265445, 2025).
cystic fibrosis (continued). "Cystic fibrosis is an autosomal recessive disease caused by deleterious mutations in the CF transmembrane conductance regulator (CFTR) gene, which encodes a chloride and bicarbonate channel." (PMID 41180002, 2025). "Cystic fibrosis is a genetic disease defined by mutations in the gene encoding the cystic fibrosis transmembrane conductance regulator CFTR, which affects chloride ion transport across cell membranes in multiple organs." (PMID 39945545, 2025). "CF, a common autosomal recessive life‐limiting disorder, is caused by mutations in the cystic fibrosis transmembrane conductance regulator (CFTR) gene." (PMID 38372567, 2024). "Cystic fibrosis is an autosomal recessive disease that is caused by mutations in the CF transmembrane conductance regulator (CFTR) gene, which codes for a chloride channel." (PMID 39040318, 2024). "Cystic fibrosis is an autosomal recessive condition caused by pathogenicvariants in the regulatory regions of the CF transmembrane conductance regulator(CFTR)." (PMID 38558018, 2024). "Complex alleles of the CFTR gene complicate the diagnosis of cystic fibrosis, the classification of its pathogenic variants, affect the clinical picture of the disease and can affect the efficiency of targeted drugs." (PMID 39408749, 2024). "CF is an autosomal recessive genetic disorder, caused by inherited mutations in the cystic fibrosis transmembrane conductance regulator (CFTR) chloride ion channel." (PMID 39654682, 2024). "Cystic Fibrosis is present due to mutations in the Cystic Fibrosis Transmembrane Conductance Regulator (CFTR) gene, the most frequent variant being p.phe508del." (PMID 38247876, 2024). "CF primarily affects cystic fibrosis transmembrane conductance regulator (CFTR) channels via disease-causing mutations in the CFTR gene, of which more than 2000 have been identified to date." (PMID 39413095, 2024). "Cystic fibrosis is caused by pathogenic nucleotide variants of the CFTR gene, which encodes the cystic fibrosis transmembrane conductance regulator (CFTR) protein." (PMID 38392563, 2024). "Cystic fibrosis is a monogenic disease caused by the dysfunction of the cystic fibrosis transmembrane conductance regulator (CFTR), an ATP-gated anion channel located at the apical side of epithelial cells, leading to multiorgan affectation." (PMID 38539900, 2024). "Cystic fibrosis is a lethal, autosomal recessive disorder caused by mutations in the CFTR gene that results in aberrant transport of chloride, bicarbonate, and sodium ions." (PMID 37918963, 2024). "CF results from mutations in the cystic fibrosis transmembrane conductance receptor (CFTR), a chloride channel that coordinates ion and fluid transport across the epithelium." (PMID 39015565, 2024). "Cystic fibrosis is a multi-system condition caused by mutations in the cystic fibrosis transmembrane conductance regulator (CFTR) gene that cause impaired production or functioning of the CFTR-protein which is essential for chloride and bicarbonate transport across epithelial cell membranes." (PMID 38717689, 2024). "Cystic fibrosis is an autosomal recessive inherited condition linked to mutation of the cystic fibrosis transmembrane conductance regulator (CFTR) gene." (PMID 41220810, 2024). "CF is caused by recessively inherited variants of the cystic fibrosis transmembrane regulator (CFTR) human gene on chromosome 7, which encodes the CFTR/ABCC7 anion channel." (PMID 39707455, 2024). "In most CF cases, symptoms manifest early with respiratory and digestive issues due to mutations in the cystic fibrosis transmembrane conductance regulator (CFTR) gene." (PMID 39328641, 2024). "Cystic fibrosis is an autosomal recessive disease caused by mutations in the ctrl gene leading a misfunction in the CF transmembrane conductance regulator (CFTR), a cAMP-regulated chloride channel expressed in epithelial cells of different tissues." (PMID 39125890, 2024).
cystic fibrosis (continued). "A genetic assessment pinpointed a detrimental cystic fibrosis transmembrane conductance regulator (CFTR) gene mutation on Exon 8, thereby confirming the presence of CF." (PMID 39328641, 2024). "The pathophysiology of CF bronchiectasis results from mutations in the cystic fibrosis transmembrane conductance regulator (CFTR) gene, which is responsible for chloride and water transport, leading to the production of thick mucus." (PMID 38762736, 2024). "Cystic Fibrosis is the commonest genetically inherited disease (1 in 4,500 newborns) and 70% of people with CF (pwCF) harbour the F508Del mutation, resulting in misfolding and incorrect addressing of the channel CFTR to the epithelial membrane and subsequent dysregulation of fluid homeostasis." (PMID 38469306, 2024). "CF is caused by mutations in the cystic fibrosis transmembrane conductance regulator (CFTR) genes, resulting in the CFTR protein becoming deficient, dysfunctional, or completely absent." (PMID 40225935, 2024). "Cystic fibrosis is a hereditary autosomal recessive disease driven by deleterious variants of the CFTR gene, leading, among other symptoms, to increased lung infection susceptibility." (PMID 39606224, 2024). "In contrast, CF is a genetic disease caused by mutations in the gene coding for the cystic fibrosis transmembrane conductance regulator (CFTR) channel." (PMID 39223101, 2024). "Caused by mutations in the cystic fibrosis transmembrane conductance regulator (CFTR) gene, CF is associated with a reduced volume of airway surface liquid overlying pulmonary epithelial cells, increased accumulation of viscous mucus, and entrapped pathogens." (PMID 38084406, 2024). "In patients with cystic fibrosis, a mutation in the CF transmembrane conductance regulator gene accumulates dry and sticky airway secretions, creating an ideal environment for the onset of pulmonary infections." (PMID 39061324, 2024). "Cystic fibrosis is a rare, life-limiting autosomal recessive genetic disorder caused by mutations in the gene encoding the chloride-conducting transmembrane channel known as CF transmembrane conductance regulator (CFTR) that regulates anion transport across multiple epithelia." (PMID 39201852, 2024). "Mutations in the cystic fibrosis transmembrane conductance regulator (CFTR) gene lead to CF, a life-threating autosomal recessive genetic disease." (PMID 38358827, 2024). "Cystic fibrosis is a monogenetic disease caused by the mutation of CFTR, a cAMP-regulated Cl− channel expressing at the apical plasma membrane (PM) of epithelia." (PMID 38666024, 2024). "Cystic fibrosis is an autosomal recessive genetic disorder resulting from mutations in the CF transmembrane conductance regulator (CFTR) gene responsible for encoding a chloride channel." (PMID 38792587, 2024). "In another well-known disease state,cystic fibrosis, patients contain loss of function mutationsin CFTR." (PMID 38980755, 2024). "In cystic fibrosis, pathogenic variants in the cystic fibrosis transmembrane conductance regulator (CFTR) gene results in system-wide debilitating consequences." (PMID 38515211, 2024). "Some, such as mutations in the CFTR gene underlying cystic fibrosis, may be tested for prenatally." (PMID 38549844, 2024). "CF results from mutations in the cystic fibrosis transmembrane conductance regulator (CFTR) gene, affecting the production of the CFTR protein responsible for the transport of chloride and bicarbonate ions across cell membranes." (PMID 38990412, 2024). "Cystic fibrosis is caused by variants in the gene encoding the cystic fibrosis transmembrane conductance regulator (CFTR), an anion selective channel present in epithelial tissues." (PMID 38888668, 2024). "CF is caused by defects in the cystic fibrosis transmembrane conductance regulator (CFTR) gene, following an autosomal recessive pattern of inheritance." (PMID 39518670, 2024).
cystic fibrosis (continued). "CF is caused by the hereditary mutation of the cystic fibrosis transmembrane conductance regulator (CFTR) gene that disrupts the transepithelial movement of ions, leading to an aberrant accumulation of thick and sticky mucus within the airways." (PMID 38652457, 2024). "The pathogenesis of CF is the result of mutations to the cystic fibrosis transmembrane conductance regulator (CFTR) protein, an apical membrane anion channel in epithelia." (PMID 38954478, 2024). "CF results from the mutation of the cystic fibrosis transmembrane conductance regulator (CFTR) gene localized in the long arm of chromosome 7." (PMID 38928397, 2024). "Cystic fibrosis is a multisystemic, autosomal recessive genetic disorder stemming from the dysfunction of the cystic fibrosis transmembrane conductance regulator (CFTR) gene that encodes for a transmembrane protein essential to the transport of chloride and bicarbonate." (PMID 39330416, 2024). "Cystic fibrosis is a life-threatening genetic disorder caused by mutations in the cystic fibrosis transmembrane conductance regulator (CFTR) gene, resulting in the accumulation of thick, sticky mucus in various organs, most notably the lungs." (PMID 39770741, 2024). "Over 1800 cystic fibrosis transmembrane regulator (CFTR) mutations associated with CF disease were identified." (PMID 39124756, 2024). "CF is a rare, monogenic disease evolved by mutations from the cystic fibrosis transmembrane conductance regulator CFTR gene." (PMID 38254715, 2024). "CF is caused by the presence of pathogenic variants of the CFTR (Cystic Fibrosis Transmembrane Conductance Regulator) gene that encodes 1480 amino acids transmembrane protein and forms cAMP-dependent chloride channel expressed by epithelial cell membranes." (PMID 38474016, 2024). "Cystic fibrosis is a genetic multisystem disorder caused by mutations in the CF transmembrane conductance regulator (CFTR) gene." (PMID 38890643, 2024). "CF is a genetic disease caused by a mutation in the cystic fibrosis transmembrane conductance regulator (CFTR), an anion channel essential for proper ion balance." (PMID 39315786, 2024). "Cystic fibrosis is the most common fatal genetic disease among Caucasian people, with over 2000 mutations in the CFTR gene." (PMID 39338347, 2024). "Cystic fibrosis is caused by mutations in the cystic fibrosis transmembrane conductance regulator (CFTR) gene which is situated on the long arm of chromosome 7." (PMID 38820269, 2024). "Cystic fibrosis is a recessive disorder that is caused by variants in the CF transmembrane conductance regulator (CFTR) gene, an ion channel that moves chloride ions across epithelial cells in many organs." (PMID 38545546, 2024). "Cystic fibrosis is a genetic disease caused by a loss of function of the CF transmembrane conductance regulator (CFTR) protein that transports chloride and bicarbonate." (PMID 39456863, 2024). "CF is an autosomal recessive genetic disease caused by mutations in the cystic fibrosis transmembrane conductance regulator (CFTR) gene, leading to airway mucus buildup and chronic infections." (PMID 38275975, 2024). "Cystic fibrosis is an autosomal recessive trait that is caused by mutations in the Cystic Fibrosis Transmembrane Conductance Regulator (CFTR) gene." (PMID 39239637, 2024). "Cystic fibrosis is a recessive inherited disorder caused by genetic mutations in the CF transmembrane conductance regulator (CFTR) gene." (PMID 39296431, 2024). "CF is a genetic disease caused by a mutation in the Cystic Fibrosis Transmembrane Conductance Regulator (CFTR) protein, located on chromosome seven at position 7q31." (PMID 39329596, 2024). "CF is a life-threatening genetic disorder caused by mutations in the cystic fibrosis transmembrane conductance regulator (CFTR) gene." (PMID 38560484, 2024).